CFTR (CF transmembrane conductance regulator)
Diseases named in the same sentence as CFTR in open-access papers (continued):
Sharing a sentence is not in itself a finding about the gene and the disease.
cystic fibrosis (continued). "Cystic fibrosis caused by mutations in the CFTR gene remains one of the most fatal hereditary disorders worldwide." (PMID 33946490, 2021). "Cystic fibrosis is a severe genetic disorder caused by mutations in the gene encoding the CF transmembrane conductance regulator (CFTR)." (PMID 33494144, 2021). "Cystic fibrosis is a common autosomal recessive genetic disorder, resulting from the defective CF transmembrane conductance regulator (CFTR) gene, which causes abnormal mucous secretions in multiple organs, notably the lungs, liver and pancreas." (PMID 34458906, 2021). "The genetic disease cystic fibrosis is caused by mutations in an important chloride channel called the CF transmembrane conductance regulator (CFTR)." (PMID 34578208, 2021). "Cystic fibrosis is a life threatening autosomal recessive disease caused by mutations in the CF transmembrane conductance regulator (CFTR) gene." (PMID 33984027, 2021). "Cystic fibrosis lung disease results from a cascade of events that begin with mutations in a single gene coding for an ion channel, CFTR, leading to defective chloride secretion and reduced airway surface liquid hydration." (PMID 33727344, 2021). "Cystic fibrosis is a genetic disease caused by a mutation(s) in the CF transmembrane regulator (CFTR), where progressive decline in lung function due to recurring exacerbations is a major cause of mortality." (PMID 33546140, 2021). "Cystic fibrosis is a life-limiting autosomal recessive condition arising from mutations in the gene encoding the CF transmembrane conductance regulator (CFTR) protein." (PMID 33296276, 2021). "Cystic fibrosis is an autosomal recessive monogenic disease caused by a mutation(s) in the CF transmembrane conductance regulator (cftr), a cAMP-regulated chloride channel gene, discovered in 1989." (PMID 33546140, 2021). "In addition, CFTR dysfunction is related to the loss of fertility and cystic fibrosis." (PMID 33406808, 2021). "Cystic fibrosis arises from mutations in the CF transmembrane conductance regulator (CFTR) gene, resulting in progressive and life-limiting respiratory disease." (PMID 33296276, 2021). "Homozygous or compound heterozygous variants in the cystic fibrosis transmembrane conductance regulator (CFTR) gene cause CF." (PMID 34842611, 2021). "Cystic fibrosis is caused by mutations in the gene encoding the CF Transmembrane Conductance Regulator (CFTR), an apical chloride channel." (PMID 33805052, 2021). "Cystic fibrosis is a lethal, monogenic disorder involving autosomal recessive mutations of the CF transmembrane conductance regulator (CFTR) gene encoding the CFTR protein." (PMID 34708042, 2021). "Cystic fibrosis is an autosomal recessive disorder caused by mutations in cystic fibrosis transmembrane conductance regulator (CFTR) gene." (PMID 33397475, 2021). "Cystic fibrosis is the most common genetic disease inherited in an autosomal recessive manner caused by mutations in the CFTR (CF transmembrane conductance regulator) gene located on the long arm of the seventh chromosome." (PMID 33669566, 2021). "Since CF is a single gene disorder due to mutations in the cystic fibrosis transmembrane conductance regulator (CFTR) gene, introducing the wild-type copy of the gene was the first therapeutic approach applied by retroviral gene transfer." (PMID 34348480, 2021). "CF is an autosomal recessive genetic disease resulting from mutations in the Cystic Fibrosis Transmembrane Conductance Regulator (CFTR) gene." (PMID 34202495, 2021). "In the PPI network of OS9, OS9 and derlin 2 (DERL2) involve in protein processing in the endoplasmic reticulum and complicate CFTR (Cystic fibrosis transmembrane conductance regulator) causes cystic fibrosis pathways, which may be associated with the prognosis of glioma with mutant PTEN." (PMID 34336645, 2021).
cystic fibrosis (continued). "Cystic fibrosis is a progressive genetic disease caused by a single-gene mutation, resulting in chemical change in the cystic fibrosis transmembrane conductance regulator (CFTR), a protein that forms a chloride channel with a critical role in mucus transportation." (PMID 34743707, 2021). "A single gene mutation called the cystic fibrosis transmembrane conductance regulator (CFTR) causes CF formation." (PMID 34261470, 2021). "CF is a disease resulting from mutations in the cystic fibrosis transmembrane conductance regulator (CFTR) gene." (PMID 34579569, 2021). "Cystic fibrosis is a recessive genetic disease resulting from mutations in the CF transmembrane conductance regulator (CFTR) gene, which exhibits pathologic consequences in a number of organs." (PMID 33783131, 2021). "CF is caused by mutations in cystic fibrosis transmembrane conductance regulator (CFTR) which encodes an anion channel." (PMID 34717611, 2021). "Loss of function of the cystic fibrosis transmembrane conductance regulator (CFTR) causes cystic fibrosis." (PMID 34514718, 2021). "Cystic Fibrosis is a genetic disease caused by mutations in the CF transmembrane conductance regulator (CFTR) gene encoding the CFTR protein." (PMID 34362426, 2021). "Cystic fibrosis is an autosomal recessive disorder caused by mutations in the CF transmembrane conductance regulator (CFTR) gene." (PMID 33868294, 2021). "CF occurs due to pathogenic variants in the gene encoding cystic fibrosis transmembrane conductance regulator (CFTR), located on chromosome 7q31.2." (PMID 33613790, 2021). "CF is caused by mutations in the cystic fibrosis transmembrane conductance regulator (CFTR) gene, which encodes a chloride (Cl−) channel." (PMID 34180343, 2021). "The survival rate of individuals with cystic fibrosis has increased considerably as a result of improvements in clinical care, as well as the introduction of successful modulator therapies for a subset of cystic fibrosis transmembrane regulator (CFTR) mutations." (PMID 33436426, 2021). "CF is caused by mutations in the cystic fibrosis transmembrane conductance regulator (CFTR)-gene leading to abnormal function of the CFTR anion channel in the epithelium of different organs." (PMID 33882893, 2021). "The most common mutation in cystic fibrosis manifests as deletion of phenylalanine at position 508 in the cystic fibrosis transmembrane conductance regulator (F508del CFTR)." (PMID 33859562, 2021). "CF is caused by loss of function mutations in the gene for an anion channel, CFTR, cystic fibrosis transmembrane conductance regulator, which is important for fluid secretion in the airways." (PMID 34552115, 2021). "Cystic fibrosis is characterized by an airway obstruction caused by a thick mucus due to a malfunctioning Cystic Fibrosis Transmembrane Conductance Regulator (CFTR) protein." (PMID 33737583, 2021). "CF is caused by a mutation in the gene encoding the cystic fibrosis transmembrane conductance regulator (CFTR) protein." (PMID 34900752, 2021). "Cystic fibrosis is a monogenic autosomal recessive disease caused by cystic fibrosis transmembrane conductance regulator (CFTR) gene mutations." (PMID 34945117, 2021). "Cystic fibrosis is an autosomal recessive condition caused by mutations in the cystic fibrosis transmembrane conductance regulator (CFTR) gene, which encodes a chloride ion channel." (PMID 34903297, 2021). "CF is an autosomal recessive condition that is caused by a mutation in the cystic fibrosis transmembrane conductance regulator (CFTR) gene." (PMID 33977021, 2021). "CF is caused by mutations in the cystic fibrosis transmembrane conductance regulator (CFTR) gene, which leads to altered secretion of chloride and bicarbonate, and buildup of abnormally thick mucus in the lungs and intestinal tract (1, –, 4)." (PMID 34339302, 2021).
cystic fibrosis (continued). "Cystic fibrosis is an inherited, life-threatening disorder caused by mutations in the gene encoding for the cystic fibrosis transmembrane conductance regulator (CFTR), an ATP-gated chloride (Cl-) channel expressed on the apical side of airway epithelial cells." (PMID 33669352, 2021). "CFTR (cystic fibrosis transmembrane conductance regulator) is well-known to be associated with cystic fibrosis." (PMID 33672345, 2021). "CF is caused by mutations in the cystic fibrosis transmembrane conductance regulator (CFTR) gene on chromosome 7, which encodes an epithelial anion channel that impacts multiple organ systems." (PMID 34221778, 2021). "CF is a complex multi-organ monogenic autosomal recessive disorder caused by a mutation in cystic fibrosis transmembrane conductance regulator (CFTR) gene on the long arm of chromosome 7." (PMID 34577628, 2021). "Cystic fibrosis is an autosomal recessive multiorgan disease caused by mutations in the cystic fibrosis transmembrane conductance regulator (CFTR) gene, occurring in nearly 1/3500 births." (PMID 33763240, 2021). "Cystic fibrosis is a genetic disease that causes absence or dysfunction of a protein named transmembrane conductance regulatory protein (CFTR) that works as an anion channel." (PMID 33922413, 2021). "Cystic Fibrosis is caused by a defect in the CF transmembrane conductance regulator (CFTR) gene responsible for epithelial ion transport." (PMID 34385926, 2021). "Cystic Fibrosis (CF; MIM: 219700) is a multi-systemic autosomal recessive rare disease caused by pathogenic, ‘CF-causing’, variants (henceforward mutations) in the Cystic Fibrosis Transmembrane Conductance Regulator (CFTR; MIM: 602421; NM_000492.3) gene." (PMID 34600583, 2021). "CF is an autosomal recessive (AR) disorder caused by mutations in the cystic fibrosis transmembrane conductance regulator (CFTR)." (PMID 34832519, 2021). "Cystic fibrosis is an autosomal recessive disorder caused by pathogenic variants in the cystic fibrosis transmembrane conductance regulator (CFTR) gene." (PMID 34740355, 2021). "Over 2100 variants have been identified in this gene (Cystic Fibrosis Mutations Database) causing CF or CFTR-related disorder (CFTR-RD) such as congenital bilateral absence of vas deferens CBAVD, pancreatitis, or bronchiectasis." (PMID 33807548, 2021). "Given that carriers of single cystic fibrosis -causing variants of the CFTR gene—CF-carriers—are more susceptible to respiratory tract infections, our aim was to determine their likelihood of undergoing severe COVID-19." (PMID 34203982, 2021). "Cystic fibrosis is a recessive genetic disease caused by mutations in a gene encoding a protein called Cystic Fibrosis Transmembrane Conductance Regulator (CFTR)." (PMID 34831067, 2021). "Patients with CF suffer from chronic lung inflammation due to immune dysregulation and thickened mucus in the lungs caused by mutation of the cystic fibrosis transmembrane conductance regulator (CFTR) gene that impacts proper chloride ion transport." (PMID 33643308, 2021). "CF is a complex multi-organ monogenic autosomal recessive disorder caused by a mutation in cystic fibrosis transmembrane conductance regulator (CFTR) gene." (PMID 34577628, 2021). "Although mutations of the cystic fibrosis transmembrane conductance regulator (CFTR) gene affect multiple organs, obstructive lung disease remains the major cause of morbidity and mortality in CF patients." (PMID 34348676, 2021). "Cystic fibrosis is a multisystem disease caused by the alteration of a unique gene located on chromosome 7 (CFTR, cystic fibrosis transmembrane conductance regulator gene)." (PMID 34836360, 2021). "Cystic fibrosis, a lethal monogenic disease, is caused by pathogenic variants of the CFTR chloride channel." (PMID 31327045, 2020).
cystic fibrosis (continued). "CF is a fatal genetic disorder caused by dysfunction of the anion transporter cystic fibrosis transmembrane conductance regulator (CFTR), which is expressed on the apical membrane of epithelial secretory cells." (PMID 31906427, 2020). "Approximately 10% of CF patients carry cystic fibrosis transmembrane conductance regulator (CFTR) nonsense mutations that cannot be treated with any FDA-approved CFTR modulators, and around half of these mutations are correctable by ABE24." (PMID 32332735, 2020). "CF is due to mutations in the gene encoding for the cystic fibrosis transmembrane conductance regulator (CFTR) anion channel." (PMID 32630227, 2020). "Cystic Fibrosis Transmembrane conductance regulator (CFTR)-modulators have been approved as a mutation-targeted personalized treatment for CF." (PMID 32234058, 2020). "Cystic Fibrosis, caused by mutations in the gene encoding CF transmembrane conductance regulator (CFTR), is the most common life-limiting, autosomal recessive monogenic disease in Caucasian populations." (PMID 32718005, 2020). "In scenario 1, CRISPR-Cas is used to edit the CF-underlying defect at the endogenous gene locus (cystic fibrosis transmembrane conductance regulator, CFTR) in all in vitro generated human embryos descending from a CF-carrier couple." (PMID 32912206, 2020). "Cystic fibrosis is the most common autosomal recessive disease in the European population caused by mutations in the gene encoding for the CF transmembrane conductance regulator protein." (PMID 32084221, 2020). "CF is caused by biallelic mutations of the cystic fibrosis transmembrane conductance regulator gene [CFTR], resulting in disrupted epithelial fluid transport in lungs, pancreas, colon, and other organs." (PMID 33438800, 2020). "CF is caused by variants in the gene encoding the cystic fibrosis transmembrane conductance regulator (CFTR)." (PMID 33182847, 2020). "Cystic fibrosis is a genetic disease caused by a mutation in the CFTR gene (cystic fibrosis transmembrane conductance regulator)." (PMID 33520731, 2020). "CF is due to mutations of the cystic fibrosis transmembrane conductance regulator (CFTR) gene that encodes a chloride channel involved in electrolytic exchanges and is associated with impairment of the mucociliary clearance." (PMID 33117730, 2020). "Cystic fibrosis is a rare autosomal recessive disorder caused by biallelic mutations in the cystic fibrosis transmembrane conductance regulator (CFTR) gene." (PMID 32539862, 2020). "Cystic fibrosis is a life-limiting, recessively inherited disease resulting from mutations in the cystic fibrosis transmembrane conductance regulator (CFTR) gene." (PMID 33325834, 2020). "The treatment of cystic fibrosis patients homozygous for the F508del mutation with Orkambi®, a combination of a corrector (lumacaftor) and a potentiator (ivacaftor) of the mutated CFTR protein, resulted in some amelioration of the respiratory function." (PMID 32244302, 2020). "It is known that the SL ceramide accumulates in the lungs of CF patients and cystic fibrosis transmembrane conductance regulator (CFTR)-deficient mice." (PMID 32183316, 2020). "Different from the genetic disease cystic fibrosis caused by the mutations in the CF transmembrane conductance regulator, it is well recognized that tobacco smoking is the main causal and primary inciter for the formation of COPD." (PMID 33250886, 2020). "CF is due to mutations in the cystic fibrosis transmembrane conductance regulator (CFTR) gene, leading to an altered sodium and chloride transport through the respiratory, biliary, gastrointestinal and reproductive tract epithelia." (PMID 33171650, 2020). "Cystic fibrosis is a lethal autosomal recessive genetic disease caused by mutation of the cystic fibrosis transmembrane conductance regulator (CFTR) gene that encodes a transepithelial chloride transporter." (PMID 33262240, 2020).
cystic fibrosis (continued). "To summarize, these studies emphasize the need to investigate expression and function of mutant CFTR in its native epithelial context in order to understand the molecular basis for disease and pharmacological responses for mutations associated with atypical Cystic Fibrosis." (PMID 32414100, 2020). "The sequencing of the whole cystic fibrosis transmembrane conductance regulator (CFTR) gene locus revealed that the patient lacks known CF-causing mutations." (PMID 33375403, 2020). "CF is caused by a mutation in the cystic fibrosis transmembrane conductance regulator (CFTR) gene leading to mucus retention in the lungs, which, through repeated infection, causes progressive and irreversible damage to the lungs." (PMID 32526938, 2020). "CF is caused by biallelic pathogenic mutations in the cystic fibrosis transmembrane conductance regulator gene (CFTR), which is mostly expressed in epithelial cells functioning as a chloride channel protein." (PMID 32539862, 2020). "CF is caused by mutations in the Cystic Fibrosis Transmembrane Conductance Regulator (CFTR) gene, first described together with its protein product in 1989." (PMID 32824306, 2020). "CF is estimated to affect >75,000 patients globally and is caused by loss-of-function mutations in the anion channel, cystic fibrosis transmembrane conductance regulator (CFTR)." (PMID 32235608, 2020). "In cystic fibrosis, another severe inherited disease caused by loss of function of the gene encoding the cystic fibrosis trans-membrane conductance regulator CFTR, approximately 10% of cases are caused by nonsense mutations." (PMID 31972957, 2020). "Cystic Fibrosis is caused by mutations in the CF Transmembrane conductance Regulator (CFTR), the only ATP-binding cassette (ABC) transporter functioning as a channel." (PMID 32630527, 2020). "CF is one of the most common inherited disorder caused by mutations in a gene coding for the Cystic Fibrosis Transmembrane conductance Regulator (CFTR) protein." (PMID 32666337, 2020). "Cystic fibrosis is an autosomal recessive disorder caused by mutations in the cystic fibrosis transmembrane regulator (CFTR) gene, located on the long arm of chromosome 7." (PMID 33009727, 2020). "A murine model based on mice carrying the most common CF mutation F508del CFTR (Cystic Fibrosis Transmembrane Conductance Regulator) also showed that excessive activation of IL-1β correlated with increased bacterial load, inflammation and lung damage." (PMID 32817626, 2020). "CF is caused by mutations in the Cystic Fibrosis Transmembrane Conductance Regulator (CFTR) gene that encodes a chloride ion transporter typically found on the apical surface of epithelial cells." (PMID 33013490, 2020). "The first proof of concept concerningPTC-readthrough inducing was represented by geneticin (G418), initially investigated in cystic fibrosis cell models harboring nonsense mutated CFTR gene." (PMID 32630050, 2020). "Cystic fibrosis is an autosomal recessive genetic disorder arising from mutations to the cystic fibrosis transmembrane conductance regulator (CFTR) gene." (PMID 32012925, 2020). "According to the Cystic Fibrosis Mutation Database, more than 2092 variants of the CFTR gene are found, and 352 of them are CF-causing." (PMID 32971794, 2020). "Cystic fibrosis, caused by biallelic inactivating mutations in the cystic fibrosis transmembrane conductance regulator (CFTR) gene, has recently been categorized as a familial colorectal cancer (CRC) syndrome." (PMID 32326161, 2020). "CF is a recessive genetic disease caused by mutations in the gene encoding the cystic fibrosis transmembrane conductance regulator (CFTR), an ion channel that conducts chloride and bicarbonate across epithelial cell membranes." (PMID 31937646, 2020). "Cystic fibrosis is a genetic disease caused by mutations in the gene encoding cystic fibrosis transmembrane conductance regulator (CFTR) protein." (PMID 33207565, 2020).